SNORD56 (small nucleolar RNA, C/D box 56)
Synonyms: U56; RNU56
Gene: Small nucleolar RNA gene on chromosome 20 (2,656,624 to 2,656,694, forward strand). Ensembl gene ENSG00000229686.
Gene Ontology:
Biological process: RNA processing
Cellular component: nucleolus
Homologues: Orthologues: macaque SNORD56 (99% identical), pig SNORD56 (96% identical), rabbit SNORD56 (96% identical), rat Snord56 (93% identical), mouse Gm23650 (92% identical), guinea pig SNORD56 (85% identical). Paralogues in human: SNORD56B (89% identical).
Diseases named in the same sentence as SNORD56 in open-access papers:
SNORD56 is named in the same sentence as 1 disease in open-access papers, as found by Europe PMC text mining. Sharing a sentence is not in itself a finding about the gene and the disease. The quoted sentences say what the papers report.
Uterine leiomyoma (1 paper, 2022). The presence of a leiomyoma of the uterus. "In diseases not related to the eyes, SNORD56 was upregulated in uterine leiomyoma." (PMID 36078146, 2022).